ST3GAL1 (ST3 beta-galactoside alpha-2,3-sialyltransferase 1)
Description:
A beta-galactoside alpha2->3 sialyltransferase involved in terminal sialylation of glycoproteins and glycolipids. Catalyzes the transfer of sialic acid (N-acetyl-neuraminic acid; Neu5Ac) from the nucleotide sugar donor CMP-Neu5Ac onto acceptor Galbeta-(1->3)-GalNAc-terminated glycoconjugates through an alpha2-3 linkage. Adds sialic acid to the core 1 O-glycan, Galbeta-(1->3)-GalNAc-O-Ser/Thr, which is a major structure of mucin-type O-glycans. As part of a homeostatic mechanism that regulates CD8-positive T cell numbers, sialylates core 1 O-glycans of T cell glycoproteins, SPN/CD43 and PTPRC/CD45. Prevents premature apoptosis of thymic CD8-positive T cells prior to peripheral emigration, whereas in the secondary lymphoid organs controls the survival of CD8-positive memory T cells generated following a successful immune response (By similarity). Transfers sialic acid to asialofetuin, presumably onto Galbeta-(1->3)-GalNAc-O-Ser (By similarity). Sialylates GM1a, GA1 and GD1b gangliosides to form GD1a, GM1b and GT1b, respectively (By similarity).
Synonyms: SIAT4A; ST3O; SIATFL; ST3GalA.1; Gal-NAc6S; ST3GalA; ST3GalIA; ST3GalIA,1
Tractability: Small molecule: a high-quality ligand is known. Antibody: UniProt places it where antibodies can reach, with medium confidence; UniProt predicts a signal peptide or a membrane-spanning region; its Gene Ontology location is reachable by antibodies, with medium confidence. PROTAC: its protein half-life has been measured; a small molecule that binds it is known.
Target class: Enzyme; Transferase
Gene: Protein-coding gene on chromosome 8 (133,454,848 to 133,572,518, reverse strand). Ensembl gene ENSG00000008513.
Subcellular location: Golgi apparatus, Golgi stack membrane; Golgi apparatus, trans-Golgi network membrane; Secreted
Pathways (Reactome):
Disease: Maturation of protein 3a; Maturation of spike protein
Metabolism of proteins: Sialic acid metabolism; Termination of O-glycan biosynthesis
Metabolism: Keratan sulfate biosynthesis
Gene Ontology:
Molecular function: beta-galactoside (CMP) alpha-2,3-sialyltransferase activity; beta-D-galactosyl-(1->3)-N-acetyl-beta-D-galactosaminide alpha-2,3- sialyltransferase; sialyltransferase activity
Biological process: ganglioside biosynthetic process; protein sialylation; glycoprotein biosynthetic process; keratan sulfate proteoglycan biosynthetic process; N-acetylneuraminate metabolic process; protein modification process; protein N-linked glycosylation; protein O-linked glycosylation via N-acetyl-galactosamine; sialylation; viral protein processing; memory B cell differentiation; negative regulation of activated CD8-positive, alpha-beta T cell apoptotic process
Cellular component: extracellular exosome; Golgi apparatus; Golgi medial cisterna membrane; Golgi trans cisterna membrane; membrane; trans-Golgi network membrane; Golgi membrane; extracellular region; Golgi cisterna membrane
Genetic constraint (gnomAD): Loss-of-function variants: 16 observed, 33.39 expected, observed/expected ratio (o/e) 0.48, 90% interval 0.32 to 0.73. The upper end of that interval is the gene's LOEUF score, 0.73, which puts it in group 2 of 6, group 1 being the genes least tolerant of losing a copy. Missense variants: 346 observed, 452.35 expected, observed/expected ratio (o/e) 0.76, 90% interval 0.7 to 0.84. Synonymous variants: 186 observed, 188.47 expected, observed/expected ratio (o/e) 0.99, 90% interval 0.88 to 1.11.
Homologues: Orthologues: chimpanzee ST3GAL1 (99% identical), macaque ST3GAL1 (98% identical), dog ST3GAL1 (89% identical), guinea pig ST3GAL1 (86% identical), pig ST3GAL1 (84% identical), rat St3gal1 (82% identical), mouse St3gal1 (81% identical), tropical clawed frog st3gal1 (55% identical), zebrafish st3gal1l (39% identical), zebrafish st3gal1 (37% identical), zebrafish st3gal1l3 (37% identical). Paralogues in human: ST3GAL2 (48% identical), ST3GAL3 (24% identical), ST6GALNAC1 (24% identical), ST6GALNAC2 (24% identical), ST6GAL2 (23% identical), ST3GAL4 (22% identical), ST3GAL5 (21% identical), ST6GAL1 (21% identical), ST3GAL6 (20% identical), ST6GALNAC4 (19% identical), ST6GALNAC6 (17% identical), ST6GALNAC5 (16% identical), and 2 more.
Diseases named in the same sentence as ST3GAL1 in open-access papers:
ST3GAL1 is named in the same sentence as 68 diseases in open-access papers, as found by Europe PMC text mining. Sharing a sentence is not in itself a finding about the gene and the disease. The quoted sentences say what the papers report.
ovarian carcinoma (20 papers, 2017 to 2026). A malignant neoplasm originating from the surface ovarian epithelium. "ST3GAL1 is also upregulated in ovarian cancer cell lines and this seems to be associated with drug resistance." (PMID 30375371, 2018). "Moreover, in clear cell type epithelial ovarian cancer, the upregulated expression of ST3GAL1 and ST3AL4 genes were both associated with reduced E-cadherin expression and increased EMT40." (PMID 30375371, 2018). "In gynecologic cancers, ST3Gal1 has been shown to promote migration, invasion, and paclitaxel resistance in ovarian cancer." (PMID 40497576, 2025). "The overexpression of ST3GAL1 was found to increase paclitaxel resistance in ovarian cancer, while the downregulation of ST3GAL1 reduced paclitaxel resistance in vitro in cells, as well as reducing the therapeutic effect of paclitaxel on tumor growth in mice." (PMID 37894470, 2023). "Their results also indicated that overexpressing ST3GAL1 promoted cell growth, migration, and invasion in ovarian cancer cells, whereas inhibiting STG3GAL1 expression had the opposite results." (PMID 36547200, 2022). "Among them, ST3GAL1 overexpression promotes epithelial-mesenchymal transition, migration, and invasion in ovarian cancer, and ST3GAL3 downregulation inhibits pancreatic cancer cell migration and invasion." (PMID 36605200, 2022). "One such study involving qRT-PCR, western blotting, and immunohistochemistry assessed the expression of sialyltransferase ST3GAL1 in ovarian cancer tissue and cell lines and found it to be upregulated." (PMID 36547200, 2022). "In ovarian cancer cells, overexpression of ST3GAL1 increased resistance to paclitaxel, whereas downregulation of ST3GAL1 produced the opposite effect." (PMID 33921986, 2021). "ST3GAL1, the sialyltransferase gene responsible for the attachment of sialic acid in the α2,3 position, has been reported to be upregulated in ovarian cancer tissue and in the SKOV-3 and OVCAR3 cell lines." (PMID 34178940, 2021). "Treatment of ovarian cancer cells with TGF-β enhanced the expression of ST3GAL1, leading to a decrease in E-cadherin levels and increase of N-cadherin and vimentin." (PMID 33921986, 2021). "Overexpression of ST3GAL1 in ovarian cancer led to transforming growth factor (TGF)-β1-induced epithelial-mesenchymal-transition, migration, and invasion, and a knockdown resulted in the opposite." (PMID 34943806, 2021). "To conclude, in the present study, we found that ST3GAL1 is upregulated in ovarian cancer tissues but the level of ST3GAL1 can vary depending on TNM grade." (PMID 30375371, 2018). "Overall our results indicate that overexpressing ST3GAL1 promotes cell growth, migration, and invasion in ovarian cancer cells whereas inhibiting STG3GAL1 expression has the opposite effect on cell growth, migration, and invasion." (PMID 30375371, 2018). "In this work, we examine the role of the sialyltransferase ST3GAL1 in ovarian cancer tissue and the human ovarian cancer cell lines SKOV-3, OVCAR3, and A2780." (PMID 30375371, 2018). "Taken together, our findings have identified a regulatory mechanism involving ST3GAL1 in ovarian cancer." (PMID 30375371, 2018). "The expression of ST3GAL1 and clinicopathological characteristics were assessed in 78 patients with ovarian cancer." (PMID 30375371, 2018). "Levels of ST3GAL1 were found to be higher in patients with TNM stage III than in those with lower grade ovarian cancer (p = 0.014)." (PMID 30375371, 2018). "After establishing that ST3GAL1 was upregulated in ovarian cancer tissue we assessed its expression in three ovarian cancer cell lines, SKOV-3, OVCAR3, and A2780, and in control NOECs." (PMID 30375371, 2018). "The mRNA expression of ST3GAL1 was significantly higher in ovarian cancer tissue than in normal tissue (p < 0.01, Student’s t-test) and protein levels were also elevated in each histopathological type of cancer compared with normal tissue." (PMID 30375371, 2018).
ovarian carcinoma (continued). "In the present study, we found that ST3GAL1 was upregulated in ovarian cancer tissues and ovarian cancer cell lines." (PMID 30375371, 2018). "Additionally, through EGFR signaling, ST3GAL1 overexpression can encourage the migratory and peritoneal spread of ovarian cancer cells." (PMID 36547200, 2022). "ST3GAL1 is overexpressed in malignant tissues, including breast and ovarian cancer." (PMID 36077781, 2022). "A further study revealed that ST3GAL1 is essential for the TGF-1-induced EMT in ovarian cancer." (PMID 36547200, 2022). "In addition, overexpression of ST3GAL1 can promote migration and peritoneal dissemination of ovarian cancer cells via the EGFR signaling." (PMID 33921986, 2021). "A further report showed that ST3GAL1 plays a crucial role in TGF-β1-induced EMT in ovarian cancer." (PMID 33921986, 2021). "Moreover, ST3Gal1 seems to also play a role in TGF-β1-induced epithelial-mesenchymal transition (EMT) in ovarian cancer cells." (PMID 34975914, 2021). "In addition to these general aspects of sialic acids, overexpression of ST3GAL1 is specifically known to increase the migration and invasion capacity in ovarian cancer." (PMID 31952476, 2020). "For a clearer understanding of ST3GAL1 involvement in ovarian cancer, we investigated whether STG3GAL1 participated in EMT." (PMID 30375371, 2018). "Herein, we use qRT-PCR, western blotting, and immunohistochemistry to assess the expression of ST3GAL1 in ovarian cancer tissue and cell lines and investigate whether it influences resistance to paclitaxel in vitro and in a mouse xenograft model." (PMID 30375371, 2018). "Taken together, our findings have identified a mechanism whereby ST3GAL1 in ovarian cancer could contribute to cytotoxic resistance and promote cell migration." (PMID 30375371, 2018). "To assess whether the expression of ST3GAL1 had the potential to influence proliferation, migration, and invasion in the ovarian cancer cells, we carried out assays with ST3GAL1 over or under-expressed." (PMID 30375371, 2018). "Recent research supports our finding that ST3GAL1 expression is increased in serous ovarian cancer and demonstrates that ST3GAL1 may regulate ovarian cancer cell migration and peritoneal dissemination via epidermal growth factor receptor (EGFR) signaling." (PMID 30375371, 2018). "However, in A2780 ovarian cancer cells, ST3GAL1 was expressed at a lower level than in normal ovarian cells." (PMID 30375371, 2018). "Moreover, the overexpression of ST3GAL1 increased resistance to paclitaxel in ovarian cancer cells and in a xenograft mouse model." (PMID 30375371, 2018). "ST3GAL1 may be a promising target for overcoming paclitaxel resistance in ovarian carcinoma." (PMID 30375371, 2018). "Therefore, ST3GAL1 may be a promising target for overcoming paclitaxel resistance in ovarian carcinoma." (PMID 30375371, 2018). "However, the function of ST3GAL1 in ovarian cancer is uncertain." (PMID 30375371, 2018). "Wu and colleagues show that sialylation through ST3GAL1 promotes cell migration, invasion and TGF-β1-induced EMT, which results in paclitaxel resistance in ovarian cancer." (PMID 39337558, 2024). "When ovarian cancer cells were treated with TGF-, ST3GAL1 was more highly expressed, which decreased the levels of E-cadherin and increased the levels of N-cadherin and vimentin." (PMID 36547200, 2022). "The ST3GAL1 enzyme has also been shown to promote cell migration, invasion, and TGF-β1-induced EMT in ovarian cancer." (PMID 36077781, 2022). "We also investigate the expression of ST3GAL1 in EMT induced by TGF-β1 and paclitaxel resistance in ovarian cancer cell lines and a xenograft mouse model." (PMID 30375371, 2018). "We found that ST3GAL1 is upregulated in ovarian cancer tissues and in the ovarian cancer cell lines SKOV-3 and OVCAR3 but downregulated in A2780 ovarian cancer cells." (PMID 30375371, 2018).
ovarian carcinoma (continued). "Three shRNA constructs were created to knockdown ST3GAL1 expression and qRT-PCR analysis was used to measure the relative ST3GAL1 expression in SKOV-3 cells, which is the ovarian cancer cell line with the highest expression of ST3GAL1." (PMID 30375371, 2018). "Functionally, ST3GAL1 promotes migration, invasion, and TGF-β1-induced EMT in ovarian cancer." (PMID 41416421, 2026). "In ovarian carcinoma, hypersialylation driven by overexpression of ST3GAL1 not only contributes to paclitaxel chemotherapy resistance but also enhances tumorigenicity." (PMID 40547037, 2025). "ST3Gal1 is also enrolled in promoting resistance to anti-cancer effects of agents, such as of adriamycin directed against chronic myeloid leukemia (CML) cell lines, paclitaxel against ovarian cancer cells, and tamoxifen and/or vandetanib against breast cancer cells." (PMID 34975914, 2021).
breast carcinoma (17 papers, 2011 to 2024). "Mechanistically, authors showed that O-linked desialylation of CD55 by ST3GAL1 silencing results in increased C3 deposition and complement-mediated lysis of breast cancer cells, enhancing sensitivity to antibody-dependent cell-mediated cytotoxicity." (PMID 33921986, 2021). "ST3GAL1 encodes a glycosyltransferase that induces aberrant glycosylation of MUC1 in breast cancer." (PMID 21339811, 2011). "Authors reported that ST3GAL1 silencing reduces tumor growth with a remarkable decrease in vascularity of MCF7 xenografts and identified the angiogenin vasorin (VASN) as the main substrate of ST3GAL1 in breast cancer cells." (PMID 33921986, 2021). "Lin and colleagues recently demonstrated that ST3GAL1-mediated O-linked sialylation of CD55, an important complement regulatory protein, acts like an immune checkpoint molecule for breast cancer cells to evade immune attack." (PMID 33921986, 2021). "In this context, it should be noted that the overexpression of ST3GAL1 is discussed to promote, for instance, tumorigenesis in breast carcinomas." (PMID 31952476, 2020). "The overexpression of ST3GAL1 has been widely studied in cellular models of breast cancer and found to be responsible for increased malignancy." (PMID 29454317, 2018). "On the one hand, GFRα1 was identified as a target protein of ST3 beta-galactoside alpha-2,3-sialyltransferase 1 (ST3GAL1), which regulates the GDNF/GFRα1/RET pathway in breast cancer cells by mediating O-linked sialylation of GFRα1 and facilitating its interaction with RET." (PMID 35582425, 2022). "Overexpression of ST3GAL-1 has been reported in types of tumors like colon and breast cancers." (PMID 26552809, 2015). "In breast carcinoma, constitutive ST3GAL-1 expression contributed to an unfavorable prognosis." (PMID 26552809, 2015). "In addition, enhanced sialylation of T antigen in breast cancer correlated with higher levels of α2,3-sialyltransferase (ST3Gal1)." (PMID 24592356, 2014). "And ST3GAL1 regulates cancer progression by affecting the activity of the TGF-β signaling pathway in glioblastoma and breast cancer." (PMID 36059802, 2022). "With respect to the O-GalNAc pathway, we observed alterations in several related glycogenes including the downregulation of GCNT4, GALNT13, GALNT16 and C1GALT1, and upregulation of ST3GAL1, ST6GALNAC4 and GAL3ST2 in Her2+ breast cancer tissue." (PMID 36282863, 2022). "Lin and colleagues showed that ST3GAL1-mediated sialylation of CD55 renders better inhibition of the complement system at C3 level and that ST3GAL1 silencing results in increased C3 deposition and increased CDC-mediated killing of breast cancer cells." (PMID 35860237, 2022). "In breast cancer cells, prostaglandin E2 (PGE2), one of the final products of the cyclooxygenase-2 (COX-2) pathway, can induce ST3GAL1 expression in both ER-positive and ER-negative cell lines." (PMID 33921986, 2021). "Silencing of ST3GAL1 decreased GDNF-induced phosphorylation of RET, AKT and ERα, and reduced GDNF-mediated breast cancer cell proliferation." (PMID 33921986, 2021). "ST3GAL1 silencing increased sensitivity to a combination of RET inhibitor vandetanib and ER inhibitor tamoxifen in ERα-positive breast cancer cells." (PMID 33921986, 2021). "In turn, GDNF induced transcription of ST3GAL1 through AKT/Sp1, revealing a positive feedback loop between ST3GAL1 and GDNF/GFRA1 signaling in breast cancer cells." (PMID 33921986, 2021). "Overexpression of ST3Gal1 under the human MUC1 promoter in a spontaneous murine breast cancer model resulted in significantly decreased tumor latency compared to mice without ST3Gal1 overexpression." (PMID 24592356, 2014).